TRPV6 (transient receptor potential cation channel subfamily V member 6)
Diseases named in the same sentence as TRPV6 in open-access papers (continued):
Sharing a sentence is not in itself a finding about the gene and the disease.
cancer (continued). "Currently, SOR-C13 has completed phase 1 clinical trial in patients with over-expressing TRPV6 cancers." (PMID 29246030, 2017). "Suggestions of a role for TRPV6 in cancers expanded with recognition of the channel in a number of different malignancies including breast, ovary, colon, thyroid and pancreas." (PMID 28150073, 2017). "TRPV6 seems to display differing roles in the progression and proliferation of cancer dependent on cellular context." (PMID 26818094, 2016). "The potential of TRPV6 as a marker to predict the clinical outcome of cancers has been well-established." (PMID 26818094, 2016). "We report that two shorter peptides, SOR-C13 and SOR-C27, derived from the C-terminus of soricidin, are high-affinity antagonists of human TRPV6 channels that are up-regulated in a number of cancers." (PMID 23554944, 2013). "The studies reported here have led to the entry of the unconjugated SOR-C13 peptide into a Phase I human clinical trial looking at its tolerability and safety in patients with advanced cancers over-expressing TRPV6." (PMID 23554944, 2013). "This implies that the calcium supplied into the cancer cell via TRPV6 channel is used to counteract the effects of 1,25-dihydroxyvitamin D3 which have to be antiproliferative in the absence or low presence of this channel." (PMID 21347289, 2011). "In contrast, TRPV6 was detected at 7.7±3.0 × 10−2 and 2.38±0.28 × 10−4 the level of B2M in human carcinoma-derived cell lines LNCaP and CaCO-2 respectively." (PMID 22163264, 2011). "Recently, it was reported that TRPV6 induced cell proliferation and took part in the resistance to apoptosis in the prostate human LNCaP cancer cells." (PMID 18452628, 2008). "TRPV6 functions as a constitutively active Ca2+ channel, and emerging evidence indicates that its overactivity underpins the progression of several human diseases, including cancer." (PMID 41198662, 2025). "We hypothesized that cancer cells induce TRPV6 expression de novo to directly benefit from tightly regulated calcium intake via TRPV6 while providing cancer cells with a selective advantage for metastasis in the calcium-abundant niche, such as bone." (PMID 40908300, 2025). "Notably, TRPV6 is overexpressed in some of the most aggressive human cancers, including leukemia, as well as breast, prostate, colon, ovarian, thyroid, and endometrial cancers, and its overexpression correlates with disease severity." (PMID 41198662, 2025). "Moreover, in recent years, several studies have attributed TRPV6 as an oncochannel in cancers of epithelial origin." (PMID 41118703, 2025). "On the other hand, there is no proof that proto-oncogenes or cancer can be caused by TRPV6 expression alone." (PMID 38534438, 2024). "The only certain thing is that TRPV6 has a direct role in the calcium-dependent growth of cancer cells, while its precise function in this process is unknown." (PMID 38534438, 2024). "TRPV6 is a highly calcium-selective channel, and thus its targeting may have a deleterious effect on the cancer cell." (PMID 36980711, 2023). "Calcium-selective oncochannel TRPV6 is the major driver of cell proliferation in human cancers." (PMID 37160865, 2023). "This also suggests a possibility for the development of more potent THCV-inspired inhibitors with better selectivity, distribution patterns, and pharmacokinetics to fill a much-needed medicinal niche for fine-tuning TRPV6-mediated activity in numerous diseases, including cancer." (PMID 37532722, 2023). "Here we report the structure of human TRPV6 in complex with the plant-derived phytoestrogen genistein, extracted from Styphnolobium japonicum, that was shown to inhibit cell invasion and metastasis in cancer clinical trials." (PMID 37160865, 2023). "Indeed, TRPV6 was found to overexpress in some of the most severe human cancers, including leukemia, breast, prostate, colon, ovarian, thyroid, and endometrial cancers." (PMID 37160865, 2023).
cancer (continued). "However, in all in vitro applications where TRPV6 stayed in its native 3D conformation, rb82 did work, and thus was tested in TRPV6 targeting of living cancer cells." (PMID 36980711, 2023). "The increased TRPV6 expression can stimulate cancer cell metastasis and generate chemoresistance." (PMID 36230965, 2022). "Finally, we validated the drug sensitive data and the importance of TRPV6 in two cancer cell lines using q-PCR assay, CCK8 assay, EdU assay and scratch assay." (PMID 35174089, 2022). "Recent developments on TRPV6 specific novel inhibitors and understandings on different drug target sites in TRPV6 may aid in the design of new therapeutic strategies targeting TRPV6 in cancer." (PMID 35163823, 2022). "Inhibition of TRPV6 by extracellular acidification might be explained considering TRPV6 expression in distinct stages of cancer progression." (PMID 35806388, 2022). "Gain variations were observed in the great majority of cancers for TRPV6, TRPV5, TRPA1, and TRPC1." (PMID 35831825, 2022). "In our experiments, we have used a panel of different cancer cell lines known to express TRPV6." (PMID 36613866, 2022). "Despite the discovery of its crucial role in cancer cell proliferation and survival in vitro, no reliable tool to detect the TRPV6 channel has been reported so far to be used in diagnostic applications in vitro." (PMID 36613866, 2022). "We next investigated how TRPV6 promotes cancer cell progression." (PMID 34413465, 2021). "The potential value of TRPV6 as a therapeutic target in cancer treatment was recently reviewed." (PMID 34360952, 2021). "It has long been known to be overexpressed in different types of cancers: breast, where it was proposed as a prognostic marker for aggressive breast cancers; prostate, with an oncogenic potential for TRPV6; colon, with a proposed protector role; thyroid, ovary, bladder, cervix, and uterus cancers." (PMID 32186440, 2020). "The intensity of TRPV6 staining was higher in invasive than in in situ carcinoma." (PMID 32887395, 2020). "However, TRPV6 was reported to be downregulated in other cancers such as esophageal, lung, and renal cancers, indicating a dual function for TRPV6 as a tumour suppressor or tumour promoter in different cancer types." (PMID 32575381, 2020). "As induction of epithelial mesenchymal transition, EMT, has been linked to calcium signaling, we wanted to test whether expression of TRPV6 channel could impact cancer progression through regulation of EMT." (PMID 32895467, 2020). "These advances have led to preclinical and clinical studies assessing TRPV6 as a therapeutic target; the selective TRPV6 inhibitor SOR-C13 has shown promise in both in vivo models of cancer and early clinical trials in patients with advanced tumours of epithelial origin." (PMID 32825277, 2020). "To test whether overexpression of TRPV6 could induce EMT-dependent cancer cell migration, we performed circular invasion assays with MDA-MB-231 cells." (PMID 32895467, 2020). "In contrast, exogenous expression of TRPV6, led to higher levels of vimentin and slug, suggesting that TRPV6-mediated calcium influx is directly linked to the levels of EMT-markers and could in this way play a role in cancer progression." (PMID 32895467, 2020). "All these linkages of calcium to various aspects of the cancer phenotype implicate TRPV6." (PMID 31897233, 2020). "As TRPV6 was expressed in a tension sensitive manner, one could assume that stiffening environment along cancer progression, plays a role in the high TRPV6 expression." (PMID 32895467, 2020). "As such, TRPV6 joins the list of ion channels that are being targeted for cancer treatment." (PMID 31897233, 2020). "Still, it is unclear how the expression of TRPV6 gene and production of protein is up regulated in these cancers and that may offer another route to exploit TRPV6." (PMID 31897233, 2020).
cancer (continued). "In conclusion, TRPV6 expression seems to determine the levels of many common EMT-linked markers in mammary epithelial cells, while the impact of TRPV6 on cancer invasion may need further studies with different types of long-term 3D-invasion assays." (PMID 32895467, 2020). "Specifically, TRPV6 is a highly Ca2+-selective channel and its activity is also known to be modulated by oestrogen, progesterone, tamoxifen and vitamin D, affecting proliferation and survival of cancer cells." (PMID 32931488, 2020). "Upon cancer progression, abnormal proliferation and elevated stiffness of the stroma could thus hypothetically induce expression of TRPV6, leading to upregulation of EMT markers." (PMID 32895467, 2020). "Overexpression of TRPV6 appears to be common in cancers of epithelial origin." (PMID 33841132, 2020). "Due to the crucial role of TRPV6 in cancer cell proliferation, metastasis development and apoptosis inhibition, TRPV6 channel may be a novel target to be used as an effective therapy against cancers." (PMID 32429050, 2020). "Furthermore, TRPV6 positively correlated with the grade of cancer: the higher the grade, the higher the TRPV6 expression." (PMID 32887395, 2020). "TRPV6 gene is frequently up-regulated in prostate, colon, and other cancer tissues." (PMID 31526479, 2019). "TRPV6 is over-expressed and promotes the proliferation and invasion in many cancers." (PMID 26818094, 2016). "Studies thus far have shown that TRPV6 plays very complicated roles among different cancer types." (PMID 26818094, 2016). "In the retrospective study, mRNA level of TRPV6 was examined in patients (N = 174) from Sun Yat-sen University Cancer Center (mRNA cohort) and protein level of TRPV6 was examined in patients (N = 218) from Linzhou Cancer Hospital (protein cohort)." (PMID 26818094, 2016). "In breast cancer cells, tamoxifen reduces expression of TRPV6 and calcium signaling, an effect that may partly explain the anti-cancer effects of this estrogen antagonist." (PMID 23554944, 2013). "Thus, upregulating TRPV6 is the way that vitamin D3 modulates cancer." (PMID 38534438, 2024). "In fact, the initial transient increase in the TRPV6 activity under rb82 action, which is still statistically significant, was followed by a sustained decrease in its activity, which may have further consequences on the TRPV6 activity in cancer cells." (PMID 36980711, 2023). "Therefore, the effects of TRPV6 may be stimulating or inhibiting depending on the cancer cell type, which can be accomplished through distinct signalling factors or pathways." (PMID 34413465, 2021). "For cancer cells, it is possible enhanced TRPV6 production could counteract reduced NFAT activity." (PMID 31897233, 2020). "In other words, the down-regulation of TRPV6 in PDAC could aid the cancer cells to evade apoptosis." (PMID 32228510, 2020). "While the literature provides hints of the role of TRPV6-related elevation of intracellular calcium in the oncology phenotype and, conversely, what its inhibition might do, downstream effects of TRPV6 inhibition on cancer cell signalling pathways and gene expression are just beginning to emerge." (PMID 31897233, 2020). "Previous studies have indicated that TRPV6 might play a protective role in some cancers." (PMID 26818094, 2016). "The TRPV6 calcium channel is the most calcium-permeable channel of the TRP family, playing an important role in both physiology and pathophysiology, like cancer initiation and progression." (PMID 37576552, 2023). "For instance, TRPV6, the epithelial Ca2+ channel modulated by the vitamin D receptor, has also been previously related to CRC and other forms of cancer." (PMID 36900391, 2023). "TRPV1 in KIRC, TRPV2 in LUSC, TRPV3 in BRCA, TRPV6 in LUAD and BRCA, while TRPV4 in KIRC and BRCA differed significantly across different cancer subtypes (P <0.05)." (PMID 35174089, 2022).
cancer (continued). "Subsequently, the CNV percentage analysis in specific cancer subtypes of Hete Amp and Hete Del showed that TRPV1-6 (except for TRPV4) in KIRP, TRPV4 in ACC, TRPV6 and TRPV5 in GBM had greater than 40% Hete Amp levels." (PMID 35174089, 2022). "Similar to TRPV6 and TRPV2 (poor prognosis with high expression in numerous cancers), high expression of the PM Ca2+ ATPase 2 (PMCA2) conferred resistance to apoptosis and was associated with a poor prognosis." (PMID 36046118, 2021). "Based on their previously well-known role in cancer and metastasis, the presence of the four ion channels (HERG/Kv11.1, TRPC1, TRPC6, and TRPV6) were screened in (BNL and 1MEA) cells using a high throughput 96-well in-cell western assay (ICW)." (PMID 31627357, 2019). "Therefore it appears that TRPV6 function may be cancer cell type specific." (PMID 27450545, 2016). "Studies have demonstrated that some other TRP channels are highly expressed in cancer cells, and the amount of protein expresssion varies with the progression from normal to tumorigenic to metastatic cells, such as TRPM1, TRPM8, and TRPV6." (PMID 27023518, 2016). "A growing number of studies demonstrate a close correlation between an overexpression of TRP channels particularly of the TRPV6 and TRPM8 families and the development of cancer." (PMID 18452628, 2008). "The TRPV6 calcium channel is absent in healthy prostate tissue, but its expression increases considerably during cancer progression." (PMID 40908300, 2025). "Many papers suggest that TRPM8, TRPV6, or TRPA1 could be either markers of PDAC or specific targets for cancer therapies based on their localization in the cell membrane, making them easily druggable." (PMID 38543130, 2024). "At the same time, its specificity to the TRPV6 channels present on the plasma membrane is its limit, as not all tumors of all cancers express TRPV6 on the cell surface." (PMID 38879621, 2024). "Not surprisingly, therefore, TRPV6 was found overexpressed in some of the most aggressive human cancer types, including breast, prostate, colon, ovarian, thyroid, endometrial cancers, and leukemia." (PMID 37838981, 2023). "Hypermethylation and survival analysis for TRPV6 in LGG and TRPV2 in DLBC, suggested that the hypermethylation status may be drivers in those cancers." (PMID 35174089, 2022). "In addition to SOCE channels, several TRP channels contribute to the migration of cancer cells, including TRP channels TRPC1, TRPM7, TRPM8, TRPV1, TRPV2, and TRPV6." (PMID 26496025, 2015). "However, the other intracellular pathways, downstream of TRPV6, are poorly studied and their significance for cancer progression is not understood." (PMID 32895467, 2020). "TRPV6 was highly expressed in estrogen receptor-negative breast cancer cells, regulating their proliferation, suggesting that TRPV6 can be a potential therapeutic target in these cancers." (PMID 29299148, 2017).
tumor (61 papers, 2009 to 2025). "TRPV6 has been implicated in neoplasia, with its level enhanced in the ovary, breast, colon, prostate and thyroid cancers." (PMID 37468801, 2023). "Upregulation of Kv11.1 expression was associated with advanced tumor grade and high expression of Ki67 proliferative marker, whereas TRPV6, TRPM8 and AQP1/AQP3 channels were positively correlated with tumor stages III and IV and large tumor size." (PMID 33178018, 2020). "TRPV6 has been implicated in tumor development and progression, and its overexpression pattern correlates with the aggressiveness of the disease." (PMID 29941865, 2018). "However, it remains uncertain if the tumor transformation of mammary epithelial cells is linked to the dysfunction of this TRPV6 regulatory component." (PMID 38534438, 2024). "Furthermore, the expression of TRPV2, TRPV4 and TRPV6 was found to increase according to the tumor stage with an association with poor prognosis, particularly in advanced stages." (PMID 39125864, 2024). "Finally, we cannot dismiss the possibility that properties of the tumor microenvironment yet to be identified increase the susceptibility of Panc-1 cells to alterations in their TRPV6 expression." (PMID 38136316, 2023). "Authors conclude that SOR peptides may be useful for detecting tumours and delivering diagnostic or therapeutic payloads, via targeting TRPV6 channels." (PMID 37468801, 2023). "Similar TRPV6 allele frequencies were found if the prostate tissue samples were grouped according to the Gleason score, 83% of the low grade Gleason tumours exhibited the homozygous b/b genotype, 89% b/b of the high grade Gleason tumours." (PMID 19857260, 2009). "In breast cancer, TRPV4 and TRPV6 are upregulated and facilitate calcium influx, which supports cell proliferation, angiogenesis, and tumour progression." (PMID 40806720, 2025). "Its activity hyperpolarizes the membrane and enhances calcium influx via TRPV6, potentially driving tumour growth." (PMID 40806720, 2025). "Since, TRPV6 expression in immunoblotting was rather weak, though detectable, we used tumor sections formed by either PC3Mtrpv6-/- or PC3Mtrpv6-/- +pTRPV6 (a clone 1, where TRPV6 expression was high) cell lines." (PMID 38879621, 2024). "We used these cell lines for in vitro and in vivo experiments to assess the effect of TRPV6 expression on the viability, proliferation, resistance, migration, and tumor growth in nude mice." (PMID 38136316, 2023). "We analyzed the expression of TRPV6 channels in tissue samples from 46 patients with PDAC of different stages and found that TRPV6 expression increased with the tumor stage and dedifferentiation status." (PMID 38136316, 2023). "We then revealed the impact of TRPV6 expression on Ca2+ influx, proliferation, apoptosis, migration, chemoresistance, and tumor growth both in vitro and in vivo." (PMID 38136316, 2023). "To lend further support to this view, we next examined the effect of TRPV6 expression on tumor growth in vivo in a mouse model." (PMID 38136316, 2023). "These stable clones were also grafted into mice to assess the role of TRPV6 channels in PDAC tumor aggressiveness in vivo." (PMID 38136316, 2023). "Intriguingly, both TRPV6 knockdown and overexpression diminished the process of tumor formation in vivo." (PMID 38136316, 2023). "Taken together, these results indicate, on one hand, that TRPV6-mediated Ca2+ entry promotes Ca2+-mediated signaling pathways, which can promote tumor progression, thus confirming the data obtained previously." (PMID 37576552, 2023). "In this study, we aimed to investigate how TRPV6 impacts PDAC aggressiveness in tumor tissue, in PDAC cell line Panc-1, and in vivo." (PMID 38136316, 2023). "TRPV6 expression was found increased with the tumor stage, from the early stages (stages I and II) to the later ones (stages III and IV)." (PMID 38136316, 2023).